BCL2 (BCL2 apoptosis regulator)
Diseases named in the same sentence as BCL2 in open-access papers (continued):
Sharing a sentence is not in itself a finding about the gene and the disease.
non-Hodgkin lymphoma (continued). "The presence of the BCL-2 protein was studied in nine non-Hodgkin's lymphomas with testicular localisation." (PMID 7819053, 1995). "Phillips and colleagues demonstrated that resistance to BCL-2 inhibition with venetoclax in non-Hodgkin's lymphoma cells could be overcome with co-treatment with A-1210477, resulting in synergy between these two drugs." (PMID 30728900, 2019). "Moreover, Bcl-2 overexpression is correlated not only with non-Hodgkin’s lymphomas and CLL, but also small cell lung and breast cancers." (PMID 30781512, 2019). "However, exclusive targeting of BCL-2 with venetoclax in relapsed or refractory non-Hodgkin lymphoma (NHL) patients has yielded only a modest 18% overall response rate with a 1-month median progression-free survival." (PMID 29269870, 2017). "In an association study between polymorphisms of - 938C/A and Thr43Ala in the BCL-2 gene and G - 248A in the BAX gene and the risk of developing non-Hodgkin lymphoma (NHL), it was reported that the - 248AG + AA genotype of the BAX gene might be susceptible genotypes for NHL." (PMID 26744613, 2016). "Non-Hodgkin’s lymphoma and solid tumors share two targets: signal transducer and activator of transcription 3 (STAT3) and BCL2 apoptosis regulator (BCL2)." (PMID 41041638, 2025). "The most frequently determined markers in the non-Hodgkin lymphoma are CD20, CD3, CD5, CD10, BCL6, BCL2, Ki-67, MYC, and cyclin D1." (PMID 40142344, 2025). "Double-hit lymphoma (DHL) is a subtype of non-Hodgkin’s lymphoma (NHL) with genomic abnormalities in MYC and BCL2 (and less frequently BCL6), leading to the overexpression of these driver oncogenes." (PMID 31752970, 2019). "SC-1, a follicular non-Hodgkin lymphoma subtype harboring chromosomal rearrangements in MYC, BCL6 and BCL2, was among the cell lines found to be most sensitive to (−)-CR-1-31-b and CMLD011580." (PMID 30718665, 2019). "Levels of Bcl-2 family members have been reported to predict response to venetoclax in AML and MM, while Bcl-2 expression did not correlate with overall response rate to venetoclax in a phase I study in non-Hodgkin lymphoma." (PMID 40701968, 2025). "The evidence indicates a reduced development of neutralizing antibodies against SARS-CoV-2 in patients with non-Hodgkin’s lymphoma undergoing active treatment, predominantly with anti-CD20 monoclonal antibodies, Bruton’s tyrosine kinase inhibitors and the Bcl2-inhibitor Venetoclax." (PMID 36672473, 2023). "In the same context, venetoclax, an orally bioavailable Bcl-2-specific BH3 mimetic, has shown greater efficacy when combined with chemotherapies such as CHOP, R-CHOP, or bendamustine among others, in patients with relapsed or refractory non-Hodgkin's lymphoma." (PMID 33312200, 2020). "With relevance to our findings, a previous study showed that high expression of Beclin-1 correlated with a good prognosis in non-Hodgkin lymphoma when the tumors were Bcl-2 low or negative expressing and positive for the autophagy marker LC3." (PMID 24885292, 2014). "IHC analysis using a non-Hodgkin lymphoma panel was performed, and subtyping was done using the Hans algorithm to classify cases as germinal center B-cell-like (GCB) or non-germinal center B. Double expressor status was defined by IHC expression thresholds for BCL2 and c-MYC." (PMID 41458681, 2025). "For example, in non-Hodgkin’s lymphoma (NHL) and melanoma, a non-intuitive link between low expression of Bcl-2 and a high AI has been associated with increased mortality, suggesting that a high AI may be independently prognostic." (PMID 33003477, 2020).
non-Hodgkin lymphoma (continued). "A higher over-expression rate of Bcl-2 was reported in HCV patients with cryoglobulinemia (MC) compared those without MC, with a further increase in patients with non-Hodgkin lymphoma (NHL)." (PMID 21526201, 2011). "Therefore, this translocation is not responsible for the presence of the BCL-2 protein in non-Hodgkin's lymphomas with testicular localisation." (PMID 7819053, 1995). "In addition, mice receiving the combination treatment showed an increased expression of Bcl2l1 (encoding the navitoclax target BCL-xL), raising the possibility that, as has been observed in models of non-Hodgkin lymphoma, increased BCL-xL levels may contribute to BCL-2/BCL-xL inhibitor resistance." (PMID 38161426, 2024). "ABT-199 selectively targets BCL-2 not BCL-XL and is active as a single agent in lymphoid malignancies such as CLL and non-Hodgkin lymphoma." (PMID 27520705, 2016). "The first synthetic BH-3 mimetic was ABT-737, a small-molecule that binds with high affinity to BCL-2, BCL-X, and BCL-W, but not MCL-1 or A1/BFL-1, and was shown to efficiently induce apoptosis at sub-micromolar concentrations in a variety of non-Hodgkin lymphoma cell lines and in primary CLL cells." (PMID 30671383, 2018).
Hyperglycemia (72 papers, 2008 to 2025). An increased concentration of glucose in the blood. "Hyperglycemia causes activation of several proteins involved in apoptotic cell death, including members of the caspase and Bcl-2 families." (PMID 40134933, 2025). "In summary, we identified a transcription factor responsible for BCL-2 expression, a signalling axis (TRM21-FOXD1-BCL-2) underlying hyperglycaemia-triggered apoptosis, and a potential treatment for deleterious diabetic complications." (PMID 38092733, 2023). "We determined the expression of Bax, Bcl-2, and cleaved caspase-3 to assess hyperglycemia-associated apoptotic cell death in the kidneys." (PMID 37237918, 2023). "CHOP deficiency markedly increased hyperglycemia-inhibited Bcl-2 expression and decreased hyperglycemia-enhanced Cleaved caspase-3 expression." (PMID 35289326, 2022). "Recently, it has been reported that hyperglycemia promotes chemoresistance by decreasing mitochondrial DNA damage, Bax/Bcl-2 and Bax/Bcl-XL ratios, and sub-G1 phase cells associated with antitumor drug-induced cytotoxicity in human colon adenocarcinoma cells." (PMID 34988025, 2021). "Hyperglycemia-induced apoptosis is associated with increasing ratios of Bax/Bcl-2 as well as caspase-3 levels." (PMID 23304209, 2012). "Hyperglycemia-induced apoptosis was associated with increased Bax expression and decreased Bcl-2 expression at protein and mRNA levels, which were partially restored by AS-IV in a dose-dependent manner." (PMID 22745830, 2012). "Additionally, several studies reported the role of hyperglycemia-induced peripheral neuropathy associated with decreased BCl-2, increased Bax, cleaved caspase-3, and cell apoptosis." (PMID 35893792, 2022). "Release of apoptotic proteins like AIF (Apoptosis Inducing factor), Endo-G (Endo nuclease-G), Bax (bcl-2 associated X), Bcl-2 (b-cell Lymhoma-2) and caspases has been well demonstrated by our group during drug induced hepatotoxicity and hyperglycemia under in vitro conditions." (PMID 28962270, 2014). "Calcitriol has also been shown to increase the level of Bcl2, exerting an anti-apoptotic effect induced by hyperglycemia, while reducing the pro-apoptotic effect of Bad and Bak in cultured mouse podocytes." (PMID 40134933, 2025). "Another study has shown that leptin protects against hyperglycemia-induced neural damage by inhibiting Bax/Bcl-2 ratio." (PMID 38980528, 2025). "It has been shown that hyperglycemia induces apoptosis by disrupting the balance between Bax and Bcl-2 proteins." (PMID 38005391, 2023). "Numerous in vivo and in vitro studies have revealed that, in contrast to the normal state, hyperglycemia increases the expression of the pro-apoptotic Bax protein (increased Bax:Bcl2 ratio)." (PMID 38004451, 2023). "In summary, we identified FOXD1 as a direct transcription factor for BCL-2 and identified a signalling axis (TRM21-FOXD1-BCL-2) underlying hyperglycaemia-induced cell apoptosis and tissue injury." (PMID 38092733, 2023). "Herein, we unexpectedly found that FOXD1 plays a crucial role in regulating hyperglycaemia-induced apoptosis by directly modulating the transcription of BCL-2." (PMID 38092733, 2023). "Previous research has shown that hyperglycemia causes mesangial cell death via oxidative stress and inflammation, marked by an increase in the BAX/Bcl-2 ratio." (PMID 37016650, 2023). "In vivo, the results show that the expressions of cleaved caspase-3, cleaved caspase-9, and Bax/bcl-2 were obviously upregulated in the DM group compared with the normal group, which indicates that hyperglycemia induced severe apoptosis." (PMID 35890121, 2022). "We also observed that hyperglycemia visibly enhanced the ratio of apoptotic cells as well as significantly reduced the Δψm and Bcl-2 protein expressions in CMECs." (PMID 34336116, 2021). "DDP downregulated Bcl-2 and Bcl-XL more pronounced under normal glycemia than hyperglycemia in Ishikawa and HEC1B cells." (PMID 34988025, 2021).
Hyperglycemia (continued). "Hyperglycemia inhibited the apoptosis of VSMCs through the upregulation of Bcl-2 family (Bcl-2, Bcl-xL, and Bfl-1) and inhibited the activation of caspase-3." (PMID 34055013, 2021). "VEGF-A-signalling through VEGFR-2 leads to the protection of dorsal root ganglion sensory neurons in models of drug (paclitaxel) or hyperglycaemia-induced neuropathies, through induction of Heat Shock Protein 90 deacetylation and increase of Bcl-2." (PMID 34649573, 2021). "Further, the ratio of Bax/Bcl-2 mRNA expression was increased in the testicular tissues of DC rats, indicating hyperglycemia-induced testicular apoptosis." (PMID 33187275, 2020). "Recently, hyperglycemia-induced apoptosis has been extensively studied on the balance of the proapoptotic protein Bax and the antiapoptotic protein Bcl2 toward apoptosis." (PMID 32089781, 2020). "It is demonstrated that Bcl-2/Bax, cleaved Caspase-3/Caspase-3 mediated hyperglycemia-induced apoptosis of SCs." (PMID 32843960, 2020). "Hyperglycaemia-induced oxidative stress increases Bax/Bcl-2 ratio, augmenting the release of cytochrome c from mitochondria to cytosol and inducing the formation of the apoptosome." (PMID 30836664, 2019). "One study demonstrated that hyperglycemia significantly reduces Bcl-2 and enhances Bax levels in beta-cells." (PMID 30116491, 2018). "Bcl-2 assessment showed a remarkable decrease in the hyperglycemia (p < 0.001), hyperglycemia + SLN containing myricitrin 1 (p < 0.01) and 3 μM (p < 0.05) groups when compared to the control." (PMID 30116491, 2018). "The addition of DOX at 5 and 10 μM for 24 h and of 5-FU at 50 μM for 72 h down regulated much more the expression of Bcl-2 and Bcl-XL in conditions of euglycemia than in hyperglycemia in both HT29 and LOVO cells." (PMID 30150934, 2018). "Nevertheless, our results showed that the ratio of Bcl-2 to Bax was significantly decreased (P < 0.05), indicating the enhanced neuronal apoptosis in hyperglycemia mice." (PMID 29892266, 2018). "Bax to Bcl-2 ratio level showed an enhancement in the hyperglycemia (p < 0.001) and hyperglycemia + SLN containing myricitrin 1 μM (p < 0.05) groups compared to the control." (PMID 30116491, 2018). "Western blot showed a concomitant increase of Cleaved Caspase-3 with hyperglycemia, but a converse reduction of Bcl-2." (PMID 30140011, 2018). "AGEs or hyperglycemia in diabetic db/db mice can increase the Bax/Bcl-2 ratio by generating superfluous ROS, which can decrease mtPTP and subsequently activate caspase-3." (PMID 30450046, 2018). "Some of the mediators of p21 protection system against hyperglycemia-induced cell death belong to the Bcl-2 family and, among them, the anti-apoptotic Bcl-2 and the pro-apoptotic Bax genes." (PMID 27530507, 2017). "PHB effectively ameliorated hyperglycemia-activated caspase-3 and decreased Bax/Bcl-2 ratio (Both P < 0.05)." (PMID 26623724, 2016). "Of note, as compared to persistent hyperglycemia, fluctuant hyperglycemia increased Bax translocation to mitochondria and caspase-3 p17 expression and reduced Bcl-2 expression to greater levels." (PMID 27496150, 2016). "Meanwhile, hyperglycaemia significantly increased myocardial caspase-3 activity (P < 0.05) and ratio of Bax/Bcl-2 (P < 0.05)." (PMID 25210949, 2014). "Hyperglycemia also affected apoptosis and its related genes at both transcriptional and translational level (Caspase-3 & 9, Bax and Bcl-2) in the liver of diabetic rats." (PMID 28962270, 2014). "HMGB1 inhibition effectively ameliorated hyperglycaemia-activated caspase-3 (P < 0.05) and decreased Bax/Bcl-2 ratio (P < 0.05)." (PMID 25210949, 2014). "In hyperglycemia mediated oxidative stress, proapoptotic (Bax, Bad etc.)and antiapoptotic (Bcl-2, Bcl-xl) Bcl-2 family proteins are involved in response to apoptosis." (PMID 25233093, 2014). "In summary, STZ-induced hyperglycemia increased the Bax/Bcl-2 ratio, caspase-3 activation, and neuronal apoptosis in the cortex and hippocampus." (PMID 23304209, 2012).
Hyperglycemia (continued). "Furthermore, BCL-2 inhibits hyperglycemia-induced lipid peroxidation and the formation of advanced glycation end products (AGEs) without altering ROS levels." (PMID 41155612, 2025). "The Western blot results showed that among the SHAMs of the NG, HG and QU groups, the band density ratio of Bax/Bcl-2 was higher in HG sham than that in NG sham (P<0.05), suggesting that hyperglycemia per se may activate the apoptotic signaling pathway." (PMID 40273147, 2025). "The relevance of VEGFR-2 mediated signaling in the neuroprotective properties of VEGF-A was confirmed in Schwann cells and in dorsal root ganglion neurons injured by hyperglycemia or by neurotoxic drug (paclitaxel), through induction of Heat Shock Protein 90 deacetylation and increase of Bcl-2." (PMID 39939241, 2025). "In a recent study, it was discovered that rosemaric extract prevented hyperglycemia-induced cellular damage by lowering the levels of various biochemical indicators of apoptosis, such as caspase-3 activation and the Bax/Bcl2 ratio, which was similar to the results of our investigation." (PMID 38004451, 2023). "Similarly, a previous study indicated that hyperglycemia induced apoptosis through the disruption in the balance between Bax and Bcl-2 proteins." (PMID 32626781, 2020). "Hyperglycemia-induced β-cell apoptosis has been extensively studied on the balance of proapoptotic Bcl-2 proteins (Bad, Bid, Bik, and Bax) and antiapoptotic Bcl family (Bcl-2 and Bcl-xL) toward apoptosis in vitro isolated islets and insulinoma cell culture." (PMID 31531118, 2019). "Furthermore, the Bax/Bcl-2 ratio, a main index for apoptosis, was significantly elevated; indicating hyperglycaemia-induced apoptosis in the testis of STZ-diabetic rats." (PMID 27869771, 2016). "GFW markedly improved deficits in spatial memory induced by hyperglycemia which may be due to reductions in the Bax/Bcl-2 ratio caspase-3 expression and neuronal apoptosis in the hippocampus and cortex." (PMID 23304209, 2012). "We observed similar alterations in Bax and Bcl-2 expression in response to hyperglycemia." (PMID 22745830, 2012). "We found that hyperglycemia increased the Bax/Bcl-2 ratio (p<0.01)." (PMID 19492079, 2009). "These researchers found that Pax4 overexpression, but not Pax4R129W, protected animals from streptozotocin-induced hyperglycemia as well as mouse islets from cytokine-induced apoptosis; these protective effects were at least partially due to a three-fold increase in the expression of Bcl-2." (PMID 39857806, 2025). "We showed that prolonged hyperglycemia and its related intracellular stresses induced profound morphological and functional mitochondrial damage as well as mitochondria-dependent apoptosis through the intrinsic cell death pathway involving BCL-2 and caspase-9 activation." (PMID 34445504, 2021). "Therefore, we next determined whether hyperglycaemia affected the levels of the proapoptotic molecule Bax and the antiapoptotic molecule Bcl-2 in diabetic rats using immunoblotting." (PMID 29682582, 2018). "Therefore, AGEs and hyperglycemia may mediate at least some of the effects of aging via the activation of NF-kB and elevation of Bcl-2 and YAP leading to the inhibition of adipogenesis." (PMID 28903400, 2017). "Western blotting assays of Bcl-xL, Bcl-2, cleaved caspase-3, and Bax further supported the idea that PBA treatment effectively inhibited hyperglycemia-enhanced apoptosis in liver IRI." (PMID 35289326, 2022).
Hyperglycemia (continued). "The current study showed that hyperglycemia results in a significant upregulation of the proapoptotic BAX gene and downregulation of the antiapoptotic Bcl-2 gene, as well as increased BAX/Bcl-2 ratio in the testes of the diabetic rats." (PMID 34458667, 2021). "To examine whether hyperglycemia-induced cell death contributed to reduced islet size in female MKP-2 KO mice, we assessed the expression of the anti-apoptotic gene, Bcl-2, in the pancreas from STZ-treated female MKP-2 KO and WT mice." (PMID 39996734, 2025). "Conversely, transgenic mice overexpressing Pax4 exhibited a significative increase in Bcl-2 mRNA but not in Bcl-xL, and they were protected from streptozotocin-induced hyperglycemia." (PMID 39857806, 2025). "Collectively, our findings provide evidence that FOXD1 is a new transcriptional regulator of BCL-2 under hyperglycaemic conditions and that an unrecognized TRIM21-FOXD1-BCL-2 axis transduces signalling related to hyperglycaemia-induced cell apoptosis and tissue injury." (PMID 38092733, 2023). "Considering the increase of the ratio Bax/Bcl-2 and Bax/Bcl-XL as an indicator of susceptibility to apoptosis, in both HT29 and LOVO cells, the state of hyperglycemia abolished the pro-apoptotic effects of DOX and 5-FU by decreasing the ratio Bax/Bcl-2 and Bax/Bcl-XL." (PMID 30150934, 2018). "Of note, hyperglycemia also increased pancreatic expression of IL-6 and IFN-γ, indicators of inflammation, leading to pancreatic apoptosis as shown by the increase in Bax, cleaved caspase-3 protein expression and the Bax/Bcl-2 ratio." (PMID 29051569, 2017). "Nonetheless, overexpression of BCL-2 in islets did not prevent autoimmune-mediated beta cell destruction and development of hyperglycaemia." (PMID 26813254, 2016). "In mouse islets hypoglycemia but not hyperglycemia increased the Bax/Bcl-2 ratio (p<0.01) (data not shown)." (PMID 19492079, 2009). "Consistent with our study and others, we observed increased JNK phosphorylation and reduced Bcl-2 expression in the absence of MKP-2, suggesting hyperglycemia-induced JNK phosphorylation promotes islet cell death." (PMID 39996734, 2025). "Moreover, hyperglycaemia reduced the expression of Bcl-2, and butein promoted Bcl-2 expression in hyperglycaemic NP cells; however, when Sirt1 was inhibited by Ex527, butein could no longer upregulate Bcl-2 expression in hyperglycaemic NP cells." (PMID 31583043, 2019).